VCAM1 (vascular cell adhesion molecule 1)
Diseases named in the same sentence as VCAM1 in open-access papers (continued):
Sharing a sentence is not in itself a finding about the gene and the disease.
Stroke (continued). "The current study provides novel data on systemic and intracranial VCAM1 in relation to stroke comorbidities, stroke severity, and recovery, as well as the role VCAM1 plays in complex protein-protein signaling pathways." (PMID 33971895, 2021). "HDLs from stroke patients, independently of their outcome, significantly limited TNFα-induced expression of VCAM1 (increase) and CLDN1 (decrease) gene expression." (PMID 32708891, 2020). "Cerebral microvascular endothelial cells are rapidly activated after a stroke and upregulate a range of pro-inflammatory factors, including VCAM-1." (PMID 33097782, 2020). "Choroid plexus tissues were collected and analyzed for Vcam1, Madcam1, Cx3cl1, Ccl2, Nt5e, and Ifnγ expression at different timepoints after stroke using qPCR." (PMID 28754163, 2017). "Using immunohistochemistry, we observed VCAM1 protein expression in CP of intact mice and 1 day after stroke." (PMID 28754163, 2017). "At 1 day after stroke, Vcam1, Madcam1, and Cx3cl1 showed upregulation (Vcam1, Madcam1, and Cx3cl1), and this change of Cx3cl1 expression remained 2 days later (Cx3cl1)." (PMID 28754163, 2017). "The predictive capability of E-selectin is valid during the first 6 h following a stroke, while that of VCAM-1 is valid between the second and third week." (PMID 26543408, 2015). "Increase of adhesion molecules expression (such as ICAM-1, VCAM-1, E-selectin and so on) has been described after stroke." (PMID 24946684, 2014). "Using MPIOs-αVCAM-1 in mice, we demonstrated that stroke induced overexpression of VCAM-1 (involved in monocyte and T-Cell diapedesis) not only in the ischemic lesion, but also in intact brain regions." (PMID 25505871, 2014). "ICAM-1 levels peak 12 hours after stroke onset and are maintained during 24 hours whereas VCAM-1 only peaks after a day in a 1-hour MCAo model." (PMID 21040547, 2010). "In addition, it was also able to significantly inhibit PAF, IL-6, TNF-α, ICAM-1, and VCAM-1, which significantly improved cognitive function, attenuated anxiety-like behaviors, and promoted post-stroke brain function and motor recovery in stroke rats." (PMID 40837062, 2025). "The downregulation of VCAM-1 improved stroke outcomes in pre-clinical models." (PMID 37660166, 2023). "It remains to be verified if aptamers corresponding to other domains of VCAM-1 could offer therapeutic effects for stroke." (PMID 37339993, 2023). "The expression of vascular cell adhesion molecule-1 (VCAM-1) is increased on CECs after stroke." (PMID 37339993, 2023). "We further evaluated if a higher dose of VCAM-1-aptamer affects stroke outcomes." (PMID 37339993, 2023). "In a follow-up study, the authors found that elevated levels of VCAM1 in intracranial blood were positively associated with infarction and edema volume, indicating that VCAM1 may play a harmful role in stroke pathology." (PMID 36834829, 2023). "For example, patients with a high risk for ischemic heart disease and stroke have hypomethylated Long Interspersed Nucleotide Element-1 (LINE-1) repeats, associated with increased circulating vascular cell adhesion molecule-1 (VCAM-1) levels." (PMID 36855111, 2023). "Using public drug databases, we curated drugs targeting those proteins in a direction compatible with a beneficial therapeutic effect against stroke based on MR estimates and identified such drugs for VCAM1, F11, KLKB1, GP1BA, LAMC2 (inhibitors) and PROC (activators)." (PMID 36180795, 2022). "Besides leakage, adhesion proteins such as intercellular adhesion molecule 1 (ICAM1) or vascular adhesion molecule 1 (VCAM1) also change within the BBB after stroke." (PMID 35054890, 2022). "SCFAs have been associated with elevated levels of systemic proinflammatory markers IL-6, TNF-α, vascular cell adhesion molecule-1(VCAM-1), IL-17, and MCP-1 after stroke, which was associated with a high disease burden at discharge and the duration of inpatient recovery." (PMID 36389714, 2022).
Stroke (continued). "For example, it was shown that the expression of vascular cell adhesion molecule-1 (VCAM-1) in the microvasculature of the ischemic area increases at day 1 with a gradual decline 3 days after stroke, and this overlapped with the distribution of the injected NPCs." (PMID 33737862, 2021). "We now show in vivo that mice lacking IL-1R1 on brain endothelial cells exhibit reduced cerebrovascular expression of ICAM-1 and VCAM-1 that is accompanied by a marked reduction in the number of neutrophils infiltrating the brain in response to stroke, supporting our previous in vitro findings." (PMID 30453020, 2019). "After stroke, many inflammation cytokines and chemokines were released into peripheral blood including vascular cell adhesion molecule 1, p-selectin, CXCR4 and SDF-1, which promote the adhesion of MSCs to the endothelium or induce the migration of MSCs to the ischemic tissue in the brain." (PMID 21733181, 2011). "Therefore, we were interested the expression of ICAM-1, MCP-1, and VCAM-1 in the astrocytes of SHRSP/IZM rats during stroke statuses such as H/R and TNF-α stimulation." (PMID 20700422, 2010). "The increases in ICAM-1 and VCAM-1 after stroke are influenced by IL-1β and TNF-α." (PMID 21040547, 2010). "Moreover, E-selectin and VCAM-1 are considered biomarkers of stroke burden." (PMID 41154610, 2025). "Given the high specificity of the VCAM-1-aptamer to CECs shown in our study, it could be utilized as a tool to gauge the degree of inflammation and tissue damage, possibly reflecting the severity of stroke." (PMID 37339993, 2023). "Vascular cell adhesion molecule 1 has been reported to be increased early after stroke and may influence peripheral mechanisms such as cell adhesion–regulated processes and may lower nitric oxide (NO) release in the vessels, thereby contributing to decreased vascular endothelial function." (PMID 32508734, 2020). "Prospective and stroke‐cohort data suggest that VCAM‐1 adds prognostic value beyond traditional factors; combining VCAM‐1 with inflammatory markers can improve model calibration and identify patients with active vascular inflammation." (PMID 41567175, 2026). "Nonetheless, to the authors’ knowledge, this represents the most comprehensive systematic review of blood-based protein biomarkers for stroke: MMP-9, TNF-alpha, VCAM-1, ICAM-1, E-Selectin, P-Selectin, L-Selectin, NSE, GFAP, S100, S100B, BNP, and NT-proBNP." (PMID 39091977, 2024). "This novel herb-based product improves motor control evaluated using the NIHSS and stroke serum biomarkers, such as MMP-9, VCAM-1, and s100β, in patients who experienced transient ischemic stroke and minor ischemic stroke." (PMID 39599732, 2024). "We performed one-hour tMCAO in mice and intravenously administered Cy5-labeled VCAM-1-aptamers, Cy5-labeled control aptamers, or PBS at 6 h post-stroke." (PMID 37339993, 2023). "In humans, elevated levels of VCAM-1 and ICAM-1 are found in the blood and in the infarcted areas of stroke patients." (PMID 36745280, 2023). "Previous studies on the effect of UCW on stroke have indicated that UCW has a transcription-activating effect on the NOS gene and a suppressing effect on the VCAM-1 gene in human endothelial cells." (PMID 35883879, 2022). "Upon their activation following stroke, the upregulated expression of major lymphocyte integrins (LFA-1, VCAM-1, VLA-1) integrins and increased avidity to their corresponding receptors on endothelial cells facilitate the rapid homing to the injured brain." (PMID 35805099, 2022). "Weaker evidence was found for GP1BA, VCAM1 and LAMC2 as potential drug targets for stroke, with evidence for colocalization in only one pQTL dataset." (PMID 36180795, 2022). "Recently, data from the BACTRAC program demonstrated that the intracranial vascular cell adhesion molecule-1 (VCAM1) was positively related to infarct volume, edema volume, and stroke severity in patients receiving MT treatment." (PMID 36247764, 2022).
Stroke (continued). "In this study, we take a novel approach by sampling both intracranial and systemic VCAM1 from human patients during ELVO stroke to investigate how it relates to comorbid conditions, stroke severity, functional recovery, and protein-protein signaling pathways." (PMID 33971895, 2021). "The alleviated systemic inflammation leads to downregulation of ICAM-1, VCAM-1, and MMP-9 in the brain, which preserves the cerebral endothelial glycocalyx and protects the BBB, resulting in protection against stroke injury." (PMID 34612696, 2021). "In the current study, the Pearson analyses showed that the serum levels of three CAMs (E-selectin, VCAM-1, and ICAM-1) were all positively correlated with infarct volume at 48 h after stroke onset in CIS patients." (PMID 32264912, 2020). "Compared to controls, stroke patients had significantly higher VEGF-A and VCAM-1 at <8 h that remained elevated at 72 h, with significantly higher VEGF-A at <8 h; ICAM-1 was significantly increased at <8 h, while S100B and E-selectin were unchanged." (PMID 32595585, 2020). "Brain endothelial cells are activated by IL-1 after stroke via binding of IL-1R1, leading to the upregulation of ICAM-1, VCAM-1 and P-Selectin expression, as well as various chemokines, resulting in neutrophil adhesion and infiltration." (PMID 30453020, 2019). "The expression of such proteins, including vascular cell adhesion molecule-1 (VCAM-1) and intracellular adhesion molecule-1 (ICAM-1), is upregulated post-stroke." (PMID 31281252, 2019). "In contrast, VCAM-1 levels have been proposed as a predictor of stroke prognosis, although they do not correlate with infarct volume or disability severity." (PMID 40066310, 2025). "Similarly, genes involved in integrin cell surface interactions including Itga10, Itgb3, Vcam1, Itgb1, Itgae, Itgb7, Itga1, Itga5, Icam1, Itgb2, Pecam1, and Icam2 were depleted in male MMP-3 KO stroke brains." (PMID 39000490, 2024). "This novel herb-based product improves motor control as evaluated using the National Institutes of Health Stroke Score (NIHSS); level of post-stroke disability; and stroke serum biomarkers, such as MMP-9, VCAM-1, and s100β, in patients who experience transient ischemic and minor ischemic stroke." (PMID 39599732, 2024). "Taken together, these data suggest that the VCAM-1-aptamer does not significantly affect mortality, functional deficits, or infarct volume in stroke mice." (PMID 37339993, 2023). "We administered 2.5 nmol of VCAM-1-aptamer (with or without Cy5 label) to male stroke mice at 6 h post-stroke compared to PBS control." (PMID 37339993, 2023). "While we detected abundant CD31-positive endothelial cells expressing VCAM1 on sections of mouse spinal cord with motor neuron disease, we did not detect any such VCAM1-positive endothelial cells in the brain of C3a- or PBS-treated mice 28 days after stroke." (PMID 36995772, 2023). "The VCAM-1-aptamer conjugated to Cy5 fluorescence did not significantly impact stroke outcomes either." (PMID 37339993, 2023). "Whether VCAM-1 and ICAM-1 imaging methods provide differential information on stroke, pathophysiology remains to be explored." (PMID 34065179, 2021). "The Chongqing Stroke Study reported that ischemic stroke patients with neurological deterioration had higher levels of soluble ICAM1 but not soluble VCAM1 compared to patients without neurological deterioration based on the NIHSS." (PMID 33971895, 2021). "The value of measuring E-selectin and vascular cell adhesion molecule-1 (VCAM-1) has only been described for predicting nearest evolution of stroke during acute phase, but it has never been assessed for long-term outcomes." (PMID 26543408, 2015). "In vivo imaging of VCAM-1 expression using molecular imaging techniques such as positron emission tomography (PET) or magnetic resonance imaging (MRI) may, therefore, allow for the non-invasive diagnosis and monitoring of stroke and inflammatory diseases." (PMID 37339993, 2023).
Stroke (continued). "However, experiments in rats and mice have shown that blocking VCAM-1 molecules with specific antibodies did not reduce the magnitude of post-stroke damage." (PMID 34868060, 2021). "Regardless of the type of stroke, these processes culminate in endothelial activation characterised by upregulation of vascular cell adhesion molecule (VCAM)-1, as well as neuronal death/neurological dysfunction, blood–brain barrier (BBB) disruption, and consequent cerebral oedema." (PMID 33097782, 2020). "However, in terms of the major adverse cardiovascular events, VCAM-1 concentration is significantly associated with cardiovascular mortality in type 2 diabetes patients, and circulating levels of soluble VCAM-1, ICAM-1 are shown to be elevated in diabetic patients with stroke." (PMID 31550292, 2019). "Therefore molecular imaging of the brain is limited to endothelial proteins (such as VCAM-1, ICAM-1, E-selectin, and P-selectin), to diseases with compromised BBB (such as stroke, multiple sclerosis or severe traumatic brain injury) and to cells capable of crossing the BBB (such as monocytes)." (PMID 25505871, 2014). "A stronger elevation of VCAM-1 and ICAM-1 expression in cerebellar endothelial cells suggested a higher interaction between inflammatory cells and vessels, which might lead the cerebellum to be more sensitive to neutrophils, the fastest-accumulated cells in infarcted regions after stroke." (PMID 35592334, 2022).
Hyperglycemia (70 papers, 2010 to 2025). An increased concentration of glucose in the blood. "In human cell culture studies, increased expressions of PAI-1 and VCAM-1 have been reported to be associated with hyperglycemia-related endothelial cell dysfunction, a process that predisposes vasculature to accelerated atherogenesis." (PMID 26111974, 2015). "In the presence of risk factors such as DM (hyperglycaemia), endothelial cells are activated to express adhesion molecules such as vascular cell adhesion molecule-1 (VCAM-1) and intercellular adhesion molecule-1 (ICAM-1) which are required for leukocyte adhesion to the endothelial surface." (PMID 22347666, 2012). "Transient hyperglycemia causes epigenetic modifications in the promoter of the NF-κB p65 subunit inducing a sustained increase in NF-κB expression and NF-κB-dependent VCAM-1 and MCP-1 expression for 6 days after restoration of normoglycemia, a phenomena termed epigenetic memory." (PMID 22489274, 2012). "Other studies link inflammatory agents, adipokines, and cell adhesion molecules—such as intercellular adhesion molecule 1 (ICAM-1) or vascular cell adhesion molecule 1 (VCAM-1)—with insulin resistance and hyperglycemia during pregnancy." (PMID 40362828, 2025). "Hyperglycemia and hyperlipidemia have also been shown to induce VCAM-1 expression in retinal vessels of mice." (PMID 38317227, 2024). "Hyperglycemia induced overexpression of vascular cell adhesion molecule-1 (VCAM-1) and P-, E- and L-selectins." (PMID 38378550, 2024). "Hyperglycemia induces adhesive molecules like VCAM-1 and ICAM-1, which contribute to damage in the retina, the neuro-vascular coupling tissue." (PMID 39635433, 2024). "Similar to other studies, our study showed that hyperglycemia increased the expression of VCAM-1, ICAM-1, and VEGF-1 in HUVEC cells." (PMID 36982499, 2023). "VCAM-1 is a cellular adhesion molecule expressed on the surface of ‘activated’ endothelial cells in response to hyperglycemia-induced oxidative stress and cytokine production in T2DM." (PMID 37759966, 2023). "In the present study, we demonstrated that hyperglycemia/high glucose increased VCAM-1 expression (E andFigure 2A) and monocyte-endothelial adhesion." (PMID 35607953, 2022). "ROS production and hyperglycemia can induce endothelial cells to overexpress vascular cell adhesion molecule-1 (VCAM-1)." (PMID 36088760, 2022). "It is reported that hyperglycemia upregulated VCAM-1 expression on blood vessels in the retina in experimental DR in animals." (PMID 35969320, 2022). "CTRP3 exhibits anti-inflammatory via attenuating hyperglycemia and hyperlipidemia-induced elevating VCAM-1 expression in the human retinal microvascular endothelial cells." (PMID 35969320, 2022). "The upregulation of VCAM-1 by hyperglycemia in endothelial cells also depends on the presence of IL-1β." (PMID 40477401, 2021). "Previously we have shown that hyperglycemia induces transient up-regulation of inflammatory cell adhesion molecules such as VCAM-1." (PMID 26206552, 2015). "T2D patients showed increased ICAM-1 and VCAM-1 plasma concentrations, which was thought to be related to hyperglycaemia." (PMID 26529237, 2015). "VCAM-1 expression is also induced under vascular stress conditions such as insulin resistance and chronic hyperglycaemia." (PMID 24499567, 2013). "Many studies indicated that NF-κB signal pathway was involved in the hyperglycemia-mediated up-regulation of gene and protein expression of endothelial adhesion molecules, including VCAM-1, ICAM-1, and E-selectin." (PMID 23311470, 2013). "Our results in wt mice show that STZ-induced hyperglycemia results in enhanced endothelial activation in mouse retinal vessels, as assessed by measurements of VCAM-1 protein expression." (PMID 20856927, 2010). "Hyperglycemia triggers an inflammatory response in the retina of normolipidemic mice and up-regulation of VCAM-1 in retinal vessels." (PMID 20856927, 2010).